PPARG (peroxisome proliferator activated receptor gamma)
Diseases named in the same sentence as PPARG in open-access papers (continued):
Sharing a sentence is not in itself a finding about the gene and the disease.
diabetes (continued). "PPARγ inhibits diabetes-induced retinal leukostasis and microvascular leakage through its role on increasing expression of endothelial nitric oxide synthase (eNOS) activity, reducing oxidative stress, inhibiting apoptosis, inflammation, and angiogenesis." (PMID 33013692, 2020). "Other studies have shown that PPARγ agonists improve beta cell function and prevent mitochondrial alterations and diabetes in obese mice and rats." (PMID 32395123, 2020). "Pioglitazone and GW9662, the widely used PPARγ agonist and PPARγ antagonist, were demonstrated to promote and inhibit PPARγ signaling in sedentary diabetes rats, respectively." (PMID 30873215, 2019). "PPARγ agonists (e.g. pioglitazone) have been widely used in the treatment of diabetes mellitus and the prevention of macrovascular events and the development of diabetes in patients with insulin resistance." (PMID 31277592, 2019). "A recent study has also revealed that idiopathic uric acid nephrolithiasis can be treated by pioglitazone, which is a peroxisome proliferator-activated receptor gamma (PPAR-γ) agonist to treat diabetes." (PMID 31557790, 2019). "Accordingly, pharmacological activation of PPARγ has emerged as an effective method for treating diabetes, atherosclerosis, and other metabolic diseases." (PMID 31019978, 2019). "Though the feasibility of therapeutically targeting the MPC in vivo in humans has yet to be fully tested, we note that PPARγ-sparing thiazolidinedione-like molecules that inhibit the MPC attenuate diabetes in rodents and are now being tested in humans." (PMID 31305240, 2019). "While the role of PPARγ in adipogenesis and diabetes has been extensively studied, little is known about PPARγ function during early embryonic development." (PMID 31741801, 2019). "Rosiglitazone, a peroxisome proliferator-activated receptor gamma (PPARγ) agonist, was approved as a conventional insulin sensitizer in the treatment of type 2 diabetes mellitus." (PMID 30699999, 2019). "As PPARγ full agonists, thiazolidinediones (TZDs), such as rosiglitazone and pioglitazone, have been widely used in treating type 2 diabetes mellitus due to their potent insulin-sensitizing effects." (PMID 31581474, 2019). "Meanwhile, some investigations found that the NF-κB inactive value of curcumin was possibly in a PPARγ-dependent pathway in many pathological conditions, including pulmonary fibrosis, myocardial infarction, diabetes, and cardiac fibrosis." (PMID 31073274, 2019). "PPARγ agonists (e.g. pioglitazone) have been widely used in the treatment of pre-diabetes and diabetes mellitus." (PMID 31277592, 2019). "As a mediator of adipogenesis, PPARγ plays a role in the progression of pathological diseases such as obesity, diabetes, atherosclerosis, cancer, and chronic inflammation." (PMID 31741801, 2019). "Our study does support the beneficial effect of PPARγ agonists on reducing proteinuria, as previously shown in hypertensive and diabetes animal models, as well as T2DM patients." (PMID 31277592, 2019). "As an important target for the generation and development of diabetes mellitus, peroxisome proliferator-activated receptor γ (PPARγ) has been widely studied." (PMID 29473866, 2018). "Following the utilization of PPARγ agonists for type 2 diabetes mellitus in improving insulin sensitivity, the pleiotropic effects of PPARγ in neurodegenerative diseases like AD have been increasingly investigated in recent years." (PMID 30420872, 2018). "SREBP1c and FOXO have been reported to play a role in transcriptional regulation of metabolism at high glucose levels, FOXO-1 in cardiac pathology in diabetes mellitus, PPARγ in lipid metabolism, and PPARs in cardiac dysfunction in diabetic cardiomypathy." (PMID 30385846, 2018). "Pioglitazone, a drug used in the treatment of diabetes mellitus, is a peroxisome proliferator-activated receptor-gamma (PPAR-gamma) agonist which increases expression of the PPAR-gamma gene, reducing glucose and subsequently reducing CVS risk." (PMID 30473975, 2018).
diabetes (continued). "PPARγ is an important target in diabetes therapy, and regulates the cell signaling of the inflammation process." (PMID 30126250, 2018). "In 2004, the angiotensin II receptor 1 antagonist telmisartan, which is to treat hypertension and diabetes, was identified as a partial agonist of PPARγ." (PMID 30012954, 2018). "Except as the key transcription factor of the adipocyte differentiation, PPARγ is also an important target of diabetes drugs." (PMID 28816006, 2018). "Diabetes treatment drugs represented by TZDs, which mainly activate PPARγ, have received widespread attention and are focuses for drug development." (PMID 30060458, 2018). "The advanced development of PPARγ agonists represents a valuable research tool for diabetes therapy." (PMID 29473866, 2018). "Thiazolidinediones (TZDs), synthetic ligands of PPARγ, have been used for the treatment of diabetes mellitus for two decades." (PMID 30079233, 2018). "The pharmacological activators of PPARγ include thiazolidinediones (TZDs), which are insulin sensitizers used in the treatment of type 2 diabetes mellitus (T2DM), despite some drawbacks." (PMID 30060458, 2018). "PPARγ agonists, thiazolidinediones, are currently used in the treatment of diabetes mellitus type 2." (PMID 27896950, 2017). "Since a type of brain-specific-diabetes is observed in AD, targeting PPARG in AD has been widely considered." (PMID 28922161, 2017). "The thiazolidinedione troglitazone is a PPARγ agonist used as an insulin sensitizer for treatment of diabetes that also exhibits weak affinity to PPARα." (PMID 28137721, 2017). "So far, several metabolic diseases including atherosclerosis, diabetes mellitus, and hepatic and renal diseases have been studied in order to test any beneficial effects of these Nrf2 and PPARγ activators on their disease progression." (PMID 28928902, 2017). "The pro-inflammatory transcription factor nuclear factor kappa B (NF-κB) is a key regulator of inflammation, while the transcription factor peroxisome proliferator-activated receptor gamma (PPARγ) is a key modulator of genes involved in diabetes development." (PMID 28837146, 2017). "Thiazolidinediones, the pharmacological activators of PPARγ, are used in patients with diabetes to decrease insulin resistance and improve glycemic control." (PMID 29093735, 2017). "The protective activity of monascin against MG-induced diabetes was shown to be mediated through positive modulation of both Nrf2 and PPARγ pathways." (PMID 28928902, 2017). "The nuclear receptor peroxisome proliferator-activated receptor γ (PPARγ) is a central signal integrator in maintaining lipid and glucose homeostasis and is used as clinical target to treat diseases such as type 2 diabetes mellitus and the metabolic syndrome." (PMID 29057944, 2017). "Accumulating evidence has shown that PPARγ has protective effects in both diabetes and atherosclerosis." (PMID 28883907, 2017). "Thiazolidinediones (TZD), a family of synthetic PPARG agonist widely used in diabetes treatment, show clear improvements in insulin sensitivity, enhanced adipocyte differentiation, reduction of leptin levels, and upregulation of adiponectin." (PMID 27579030, 2016). "PPARγ agonist rosiglitazone has proven effective in the treatment of diabetes and vascular diseases." (PMID 27351287, 2016). "In the clinical practice, the specific ligands of PPARγ have been accepted for treatment of diabetes mellitus." (PMID 27293418, 2016). "Treatment of type 2 diabetes mellitus depends on oral hypoglycemic medications that contain peroxisome proliferator activated receptor gamma (PPAR-γ) and thiazolidinediones." (PMID 28228803, 2016). "PPARγ is a primary target for thiazolidinedione-structured insulin sensitizers like pioglitazone and rosiglitazone employed for the treatment of type 2 diabetes mellitus." (PMID 27955667, 2016).
diabetes (continued). "In terms of the relationship between miR-27a and PPARγ in diabetes, we design the present study to delve into the role of miR-27a in the progression of diabetic DN." (PMID 27351287, 2016). "Human cancer is enhanced by PPARγ loss-of-function mutations, but inhibited by PPARγ agonists such as TZD diabetes drugs including rosiglitazone." (PMID 27692066, 2016). "Exercise training with PPARγ agonist is expected to increase glucose uptake and improve insulin sensitivity in skeletal muscle of patients with diabetes." (PMID 27508153, 2016). "Synthetic PPARγ stimulators such as thiazolidinediones (TZDs) are widely used for the treatment of patients with type 2 diabetes mellitus." (PMID 27401457, 2016). "Thiazolidinedione, also known as peroxisome proliferator-activated receptor-gamma (PPARg) agonists, have been clinically introduced as oral antidiabetics in type 2 diabetes mellitus." (PMID 27613845, 2016). "Overall, the current study suggests that curcumin act as a potent regulator of PPARγ thereby alters the most contributing factors that protect against metabolic disorders leading to diabetes mellitus." (PMID 27777867, 2016). "Synthetic PPARγ agonists are used to improve insulin sensitivity in patients with diabetes mellitus; however, their use is limited by fluid retention." (PMID 27517916, 2016). "For example, the thiazolidinediones, PPARγ agonists, have been widely used for the treatment of type 2 diabetes mellitus owing to their effectiveness in lowering blood glucose levels." (PMID 27769068, 2016). "Thiazolidinedione (TZD), a specific peroxisome proliferator-activated receptor γ (PPARγ) agonist, was developed to control blood glucose in diabetes patients." (PMID 27047938, 2016). "TZDs that target PPARG are used to increase insulin sensitivity and reduce glycemia in the treatment of diabetes, and, additionally, PPARG activation has shown protective effects on the vasculature." (PMID 26697060, 2015). "There is increasing evidence that PPARγ was involved in AGEs-related disease, including diabetes and diabetes-related complications, cardiovascular disease, non-alcoholic fatty liver disease (NAFLD), cognitive dysfunction and dementia, and OA." (PMID 26024533, 2015). "CTRP9 downregulation by TNF-α-initiated oxidative PPARγ suppression contributes to the exacerbated heart injury in diabetes." (PMID 26457306, 2015). "Among the clinical drugs used in the treatment of type 2 diabetes mellitus, thiazolidinediones, such as rosiglitazone (Ros) and pioglitazone, can be used as PPARγ agonists to significantly reduce hypoglycemia and improve the sensitivity to the insulin pathway." (PMID 25574213, 2015). "Accordingly, ligands with high inhibitory effects on PPARγ phosphorylation by CDK5 that lack classical agonism are optimal drug candidates for diabetes." (PMID 26183621, 2015). "Limited information is available on the effects of PPARγ agonists in models that combine diabetes and CVD." (PMID 25785279, 2015). "The deleterious effects of diabetes on mature endothelium and bone marrow-derived proangiogenic cells can be favorably modulated by PPARγ agonists." (PMID 25361524, 2014). "Recent studies suggest that activators of PPARγ not only modify metabolic disturbances but also protect vascular function in diabetes." (PMID 24524207, 2014). "Some synthetic PPAR ligands have been widely used in the treatment of dyslipidemia (e.g., fibrates–PPARα activators) and diabetes mellitus (e.g., thiazolidinediones–PPARγ agonists)." (PMID 25158235, 2014). "Thiazolidinediones are oral diabetes medications that selectively activate peroxisome proliferator-activated receptor gamma and have potent anti-inflammatory properties." (PMID 25024717, 2014). "RSG, an agonist of PPARγ, exerts multifunction via the stimulation of PPARγ on a number of cell types and is used clinically to treat type 2 diabetes mellitus." (PMID 25371737, 2014).
diabetes (continued). "In summary, activation of PPARγ with rosiglitazone improves angiogenic potential of PACs and endothelial cells, impaired in diabetes." (PMID 25361524, 2014). "Human and animal data link PPARG hypermethylation to reduced PPARγ expression that is observed in cases of diabetes, breast cancer, and hyperandrogenic PCOS." (PMID 24649863, 2014). "Synthetic ligands are widely used in the treatment of dyslipidemia (e.g. fibrates - PPARα activators) or in diabetes mellitus (e.g. thiazolidinediones - PPARγ agonists)." (PMID 24524207, 2014). "The mRNA coding for PPARγ increased in intra-abdominal WAT during diabetes and decreased during insulin replacement, that is the exact opposite of adipogenesis." (PMID 25170835, 2014). "Taken together, these results demonstrate that genes centrally involved in the regulation of lipid metabolism, srebp1c, PPARγ and PPARα, Elovl4 and Elovl2 have daily rhythms of expression profile in the retina and their daily rhythms are perturbed by diabetes." (PMID 24736612, 2014). "This class of drugs acts as a potent agonist to the nuclear receptor peroxisome proliferator-activated receptor-gamma (PPARγ), and has been used clinically as an insulin sensitizer in patients with type 2 diabetes mellitus." (PMID 25411800, 2014). "To investigate the effect of some srRNAs correlated with diabetes on PPARγ, we transfected PPARγ promoter luciferase reporter with the indicated srRNA inhibitors into Hepa 1–6 cells." (PMID 23418607, 2013). "Genetic deficit or pharmacological blockade of angiotensin receptor 1 (AT1R) attenuates atherosclerosis and improves endothelial function in experimentally induced diabetes in ApoE−/− mice via peroxisome proli-ferator-activated receptor γ (PPARγ) pathway." (PMID 23547749, 2013). "There have been numerous studies demonstrating relationships between the posttranscriptional covalent modifications of PPARγ (through phosphorylation and sumoylation of said protein) to the progression of metabolic deteriorations, including diabetes." (PMID 24324517, 2013). "Some genes are reproducibly found in follow-up studies, such as genes related to diabetes including the peroxisome proliferator-activated receptor-γ (PPARG)." (PMID 24225222, 2013). "In summary, we have demonstrated that EGFR inhibitors prevent upregulation of pathways that are implicated in the sodium and water retention seen in patients with diabetes mellitus and exacerbated by the use of PPARγ agonists." (PMID 23533381, 2013). "PPARγ agonists and antagonists participate in the regulation of lipid metabolism, they play an important role during atherosclerosis, diabetes, and they also have a critical role in the regulation of growth of cancer cells." (PMID 23476786, 2013). "PPARγ is reported to act as a key transcription factor in energy homeostasis, cardiovascular disease, and diabetes." (PMID 23936431, 2013). "This novel TZD has low affinity for binding and activation of PPARγ and has insulin-sensitizing effects in mouse models of diabetes and ability to lower glucose in Phase 2 clinical trials." (PMID 23650507, 2013). "INT131, for example, a novel, nonthiazolidinedione (TZD), selective peroxisome proliferator-activated receptor gamma (PPARγ) modulator, is in development by InteKrin Therapeutics Inc. for the treatment of type 2 diabetes mellitus." (PMID 25374688, 2013). "PPARγ agonists thiazolidinediones (TZDs) and PPARα agonist fibrates are widely used as pharmacological agents in the treatment of diabetes and dyslipidemia, respectively." (PMID 23594962, 2013). "Pharmacological activation of PPARγ improves insulin resistance in diabetes and has been reported to decrease liver damage in NAFLD by restoring adipose tissue insulin sensitivity, decreasing FFA flux to the liver." (PMID 23394097, 2013). "PPARγ agonists have been effective in treatment of diabetes, with some of the effects of such drugs due to actions on fat cells." (PMID 23799023, 2013).
diabetes (continued). "Thiazolidinediones (TZD) are synthetic exogenous agonists of peroxisome proliferator-activated receptor-γ (PPARγ) and are used in the treatment of type 2 diabetes mellitus (T2DM)." (PMID 23577024, 2013). "Peroxisome proliferator-activated receptor-γ (PPARγ) agonists such as rosiglitazone and pioglitazone are used to improve insulin sensitivity in patients with diabetes mellitus." (PMID 23577024, 2013). "The peroxisome proliferator-activated receptor-gamma (PPARγ) agonist pioglitazone is an insulin-sensitizing agent that is currently used in the treatment of type 2 diabetes mellitus." (PMID 23139771, 2012). "Lastly, because PPARγ function is important in regulating insulin sensitivity and polymorphisms in PON2 have been associated with diabetes, we evaluated associations with fasting blood glucose levels." (PMID 22860094, 2012). "We have previously shown that treatment of diabetic mice with the PPARγ agonists, rosiglitazone, is able to reduce renal hypertrophy associated with STZ diabetes and uninephrectomized db/db mice." (PMID 22448165, 2012). "Together with other PPARγ agonists, they are used or are under studies for the treatment of oxidative stress-related diseases such as diabetes, vascular diseases, Parkinson's, Alzheimer's, nonalcoholic steatohepatitis (NASH), and Huntington's." (PMID 22481913, 2012). "A number of studies have suggested that PPARγ agonists have direct renoprotective actions in experimental diabetes." (PMID 22448165, 2012). "PPARG activates differentiation of precursor cells of adipocytes to the small-sized adipocytes, which secrete factors that prevent diabetes mellitus." (PMID 22937051, 2012). "It would be intriguing to investigate the roles of possible interaction of the AT2 receptor and PPARγ in the pathogenesis of diabetes." (PMID 23155382, 2012). "Thiazolidinediones (TZDs) are synthetic PPARγ (peroxisome proliferator-activated receptor gamma) agonists and a class of drugs for diabetes mellitus type 2 that can decrease blood sugar efficiently by enhancing insulin sensitivity." (PMID 22135675, 2011). "PPARγ is a ligand-activated transcription factor that regulates diverse biological activities and plays major roles in many diseases, including diabetes mellitus, metabolic syndrome, and atherosclerosis." (PMID 22190905, 2011). "Peroxisome proliferator-activated receptor-gamma (PPAR-γ) agonists were developed originally for the treatment of diabetes but these agents also have been known to have potential cardio-protective effects." (PMID 22140576, 2011). "The treatment with PPARγ agonist (CZ) and anti-oxidant (tempol) mitigates oxidative stress and thereby ameliorates diastolic dysfunction in diabetes." (PMID 20828387, 2010). "This study was designed to investigate association between Hcy and glucose in structural and functional remodeling of endocardium by defining their link to PPARγ and NO metabolism in diabetes." (PMID 20828387, 2010). "PPARγ agonist reduces tissue homocysteine levels and is reported to ameliorate homocysteine-induced deleterious vascular effects in diabetes." (PMID 20613990, 2010). "Based on our findings, we conclude that in diabetes, HHcy antagonizes PPARγ and induces production of oxygen radicals that enhances MMP-9 and inhibits TIMP-4, which in turn causes matrix remodeling, E-M uncoupling and fibrosis impairing diastolic functions." (PMID 20828387, 2010). "The critical role of PPARγ in diabetes and cardiovascular diseases suggest that it can be used as a therapeutic target for diabetic cardiomyopathy." (PMID 20828387, 2010). "Thiazolidinediones (TZDs) are PPARγ agonists, currently used for the treatment of insulin resistance and type 2 diabetes mellitus, while fibrates are mainly PPARα agonists that are efficient in lowering elevated triglyceride concentrations." (PMID 19331671, 2009).